DOCK5 (dedicator of cytokinesis 5)
Description:
Guanine nucleotide exchange factor (GEF) for Rho and Rac. GEF proteins activate small GTPases by exchanging bound GDP for free GTP (By similarity). Together with ELMO1, activates RAC1; the activity is stimulated by RHOG. Along with DOCK1, mediates CRK/CRKL regulation of epithelial and endothelial cell spreading and migration on type IV collagen.
Synonyms: FLJ21034
Tractability: Small molecule: a structure with a bound ligand is known. Antibody: UniProt places it where antibodies can reach, with high confidence; its Gene Ontology location is reachable by antibodies, with high confidence. PROTAC: ubiquitination databases record sites on it; its protein half-life has been measured; a small molecule that binds it is known.
Gene: Protein-coding gene on chromosome 8 (25,184,689 to 25,418,082, forward strand). Ensembl gene ENSG00000147459.
Subcellular location: Cytoplasm; Cell membrane; Cell projection, podosome
Subcellular location (Human Protein Atlas): Cytosol
Pathways (Reactome):
Signal Transduction: RAC1 GTPase cycle; RHOG GTPase cycle
Hemostasis: Factors involved in megakaryocyte development and platelet production
Gene Ontology:
Molecular function: protein binding; guanyl-nucleotide exchange factor activity; small GTPase binding; GTPase activator activity
Biological process: negative regulation of vascular associated smooth muscle contraction; positive regulation of epithelial cell migration; positive regulation of substrate adhesion-dependent cell spreading; positive regulation of vascular associated smooth muscle cell migration; cell migration; myoblast fusion; Rac protein signal transduction; small GTPase-mediated signal transduction
Cellular component: cytoplasm; cytosol; plasma membrane; podosome
Genetic constraint (gnomAD): Loss-of-function variants: 125 observed, 213.48 expected, observed/expected ratio (o/e) 0.59, 90% interval 0.5 to 0.68. The upper end of that interval is the gene's LOEUF score, 0.68, which puts it in group 2 of 6, group 1 being the genes least tolerant of losing a copy. Missense variants: 1,974 observed, 2,196 expected, observed/expected ratio (o/e) 0.9, 90% interval 0.87 to 0.93. Synonymous variants: 798 observed, 797.7 expected, observed/expected ratio (o/e) 1, 90% interval 0.94 to 1.06.
Homologues: Orthologues: macaque DOCK5 (99% identical), chimpanzee DOCK5 (98% identical), dog DOCK5 (96% identical), rat Dock5 (94% identical), mouse Dock5 (94% identical), pig DOCK5 (94% identical), rabbit DOCK5 (94% identical), guinea pig DOCK5 (93% identical), tropical clawed frog dock5 (74% identical), zebrafish dock5 (70% identical), Caenorhabditis elegans ced-5 (27% identical), Drosophila melanogaster Zir (15% identical), and 3 more. Paralogues in human: DOCK1 (65% identical), DOCK2 (54% identical), DOCK3 (37% identical), DOCK4 (36% identical), DOCK11 (17% identical), DOCK10 (17% identical), DOCK7 (17% identical), DOCK9 (16% identical), DOCK8 (16% identical), DOCK6 (16% identical).
Diseases named in the same sentence as DOCK5 in open-access papers:
DOCK5 is named in the same sentence as 36 diseases in open-access papers, as found by Europe PMC text mining. Sharing a sentence is not in itself a finding about the gene and the disease. The quoted sentences say what the papers report.
Obesity (6 papers, 2017 to 2024). Accumulation of substantial excess body fat. "Another switch gene associated with low physical activity, DOCK5, is associated with severe obesity in children and adults." (PMID 35682902, 2022). "Other noteworthy genes in our candidate list were APPL2, an adiponectin receptor associated with overweight and obesity in a Chinese population, DOCK5, a susceptibility gene for severe obesity, and SLC30A8, a zinc efflux transporter implicated in type 2 diabetes and obesity in Asians." (PMID 38355434, 2024). "DOCK5 has been reported associated with severe obesity and regulate hepatic insulin resistance." (PMID 38110883, 2023). "Deletion of DOCK5 in mice promoted obesity, insulin resistance, and altered glucose metabolism via activation of the mTOR/S6K1 pathway." (PMID 35682902, 2022). "One such tissue is the liver, where DOCK5 activity increases energy expenditure and insulin signaling by impeding mammalian target of rapamycin complex (mTORC1), linking DOCK5 downregulation to obesity." (PMID 33684443, 2021). "Finally, two novel genes, DOCK5 and PER3, which are involved in the regulation of the Akt/MAPK pathway and circadian rhythm, respectively, have VNTRs and INDEL that might be associated with obesity." (PMID 28615046, 2017).
osteosarcoma (4 papers, 2010 to 2014). A usually aggressive malignant bone-forming mesenchymal neoplasm, predominantly affecting adolescents and young adults. "Significant chromosome loss and underexpression of DOCK5 have been reported in osteosarcoma." (PMID 24533689, 2014). "Interestingly, in our recent study we showed that DOCK5 is located in the most significant region of copy number loss in osteosarcoma 8p21.2-p21.3 along with the TNFRSF10A gene, for which we see an overall trend of loss of expression in our current study." (PMID 20465837, 2010). "Recently, DOCK5 expression was shown to be down-regulated in osteosarcoma." (PMID 25551557, 2014). "These were, in addition to the known tumor suppressor genes PTEN and DOCK5 and the known oncogene MYC, in total 8 candidate tumor suppressor genes and 4 candidate oncogenes as potential new driver genes in osteosarcoma tumorigenesis." (PMID 25551557, 2014).
breast carcinoma (3 papers, 2017 to 2025). "Deletions in three genes were associated with increased risk of breast cancer (DOCK5, P = 3 × 10-3; OR4C11, P = 2 × 10-2; and OR4P4, P = 3 × 10-2). qPCR did not confirm the small 646-base-pair deletion at the DOCK5 locus." (PMID 28302160, 2017). "These screens identified the focal adhesion RacGEF DOCK5 (dedicator of cytokinesis 5) as essential for YAP/TAZ translocation in drug-resistant metastatic breast cancer cells." (PMID 40353692, 2025). "A genome-wide association study of the cases and controls identified deletions overlapping three gene regions (DOCK5, 6.9-fold, P = 0.003; OR4C11, 2.6-fold, P = 0.02, and OR4P4, 2.4-fold, P = 0.03) that were associated with an increased risk of breast cancer after accounting for multiple testing." (PMID 28302160, 2017). "Furthermore, the inhibition of DOCK5 reduces invasiveness and tumor burden in mice injected with MDA-MB-231 breast cancer cells." (PMID 36551595, 2022).
diabetes (2 papers, 2022 to 2024). "Interestingly, DOCK5 is overexpressed in the substantia nigra of PD patients, and diabetes is associated with the development of PD." (PMID 35682902, 2022).
esophageal cancer (2 papers, 2020 to 2024). A primary or metastatic malignant neoplasm involving the esophagus. "The biogenesis of circ-DOCK5 is inhibited in esophageal cancer by ZEB1." (PMID 38733529, 2024).
glioma (2 papers, 2022 to 2025). A benign or malignant brain and spinal cord tumor that arises from glial cells (astrocytes, oligodendrocytes, ependymal cells). "As tumorigenesis progresses, this subpopulation differentiates into other subtypes, eventually becoming C0 DOCK5+ or C2 NUSAP+ glioma cells." (PMID 39975552, 2025).
head and neck squamous cell carcinoma (2 papers, 2020 to 2023). A squamous cell carcinoma that arises from any of the following anatomic sites: lip and oral cavity, nasal cavity, paranasal sinuses, pharynx, larynx, and salivary glands. "Previously, we identified an oncogenic splicing variant of DOCK5 in head and neck squamous cell carcinoma (HNSCC); however, the mechanism for the generation of this specific DOCK5 variant remains unknown." (PMID 37434235, 2023).
acral melanoma (1 paper, 2023). "Recently, CRK‐Like (CRKL) was found to be amplified in acral melanoma, where its protein product is bound to DOCK1 and DOCK5." (PMID 36271211, 2023).
adolescent idiopathic scoliosis (1 paper, 2021). A scoliosis with no known cause arising in adolescent. "Intronic variation in DOCK5 also shows association (p < 5.0 × 10−8) with other bone phenotypes, such as heel bone mineral density and adolescent idiopathic scoliosis." (PMID 34450027, 2021).
Ataxia (1 paper, 2020). Ataxia refers to impaired coordination of voluntary muscle movement. "Other genes are related to cytoskeleton remodeling, including Cdh4, Pcdh9, Dock5, Dock3 for the proprioceptors (mutation of Dock3 is known to results in ataxia) and Stom and Pdlim1 for mechanoreceptors, as well as ion channels (Asic1 and Kcnip2 for proprioceptive fate)." (PMID 32826903, 2020).
central obesity (1 paper, 2023). "Another copy number deletion associated with early central obesity (truncal fat mass) was an 18.5 kb deletion in intergenic region on chromosome 8 (dbVar ID: nssv15929560) that was placed upstream of DOCK5 (Dedicator Of Cytokinesis 5) gene." (PMID 38110883, 2023).
esophageal squamous cell carcinoma (1 paper, 2025). Esophageal squamous cell carcinoma (ESCC) is a type of esophageal carcinoma (EC) that can affect any part of the esophagus, but is usually located in the upper or middle third. "Circ‐DOCK5 is downregulated in esophageal squamous cell carcinoma (ESCC) tissues, and it sponges miR‐627‐3p, which inhibits TGF‐β2 expression." (PMID 40356340, 2025).
influenza infection (1 paper, 2017). "We have further evaluated the potential effect of influenza proteins on DOCK5 and identified cellular functions relevant for the influenza life cycle." (PMID 29214055, 2017). "Similar to some known host factors, DOCK5 moderately compromises influenza replication when using siRNA depletion." (PMID 29214055, 2017). "Compared to the modulation of mRNA processing and splicing induced by NS1, DOCK5 seems to be required for splicing of genes relevant for the influenza life cycle." (PMID 29214055, 2017). "We further explored if and how gene splicing affected by influenza infection differs from gene splicing potentially induced by DOCK5-modulated splicing processes." (PMID 29214055, 2017). "In particular, the overlap is enriched for influenza virus host factors, indicating that DOCK5 may be required for the regulation of mRNA processing and splicing of genes relevant for the influenza life cycle." (PMID 29214055, 2017). "We sought to comprehensively examine the role of DOCK5 during influenza infection." (PMID 29214055, 2017). "Two members of the top-ranked module, MDM2 and DOCK5, are most connected across all 12 co-expression networks and they were predicted to be the top drivers of the gene networks and potential host factors for influenza infection." (PMID 29214055, 2017). "Thus, overall evidence indicates that DOCK5 plays an important role in the gene-regulatory networks that potentially modulate host processes required for influenza infection by regulating intra-cellular trafficking and splicing, as well as subverting host defenses." (PMID 29214055, 2017). "As a functional DOCK5 is absent in DOCK5-ko, so are the DOCK5-dependent processes during influenza infection." (PMID 29214055, 2017).
Intellectual disability (1 paper, 2024). "The increased elongation phenotypes observed in ASD and intellectual disability (ID)-associated Semaphorin-5A (Sema5A) Arg676-to-Cys [p.R676C] were also mediated by Dock5 signalosome molecules." (PMID 38666924, 2024).
leukemia (1 paper, 2025). A malignant (clonal) hematologic disorder, involving hematopoietic stem cells and characterized by the presence of primitive or atypical myeloid or lymphoid cells in the bone marrow and the blood. "As expected, several previously reported genes with abnormal methylation in leukemias such as CPEB1, BLK, FLT3, ZCCHC7, EBF1, HDACs, IKZF1, RB1, CDK6, DOCK5, DPP10, MUC4, JAKs, KIT, KRAS, LINC01013, MAD1L1, NOTCH1, and STATs, among others, were also detected." (PMID 41226303, 2025).
lung carcinoma (1 paper, 2022). "Given the important role of DOCK5 in osteoclasts and various diseases such as cancer, we further validated the RNA dependence of DOCK5 discovered by mass spectrometry using Western blot quantification in A549 lung cancer cells." (PMID 36551595, 2022).
osteoporosis (1 paper, 2017). A condition of reduced bone mass, with decreased cortical thickness and a decrease in the number and size of the trabeculae of cancellous bone (but normal chemical composition), resulting in increased fracture incidence. "Here, we characterized the mechanism of inhibition of human DOCK5 by C21, a small molecule that inhibits mouse Dock5 in cells and blocks bone degradation in mice models of osteoporosis." (PMID 29089502, 2017).
ovarian carcinoma (1 paper, 2020). A malignant neoplasm originating from the surface ovarian epithelium. "Among all negatively correlated co-expression genes, ANHAK (6th) and DOCK5 (7th) exhibited correlations with ovarian cancer." (PMID 33585454, 2020).
Parkinson disease (1 paper, 2014). A progressive degenerative disorder of the central nervous system characterized by loss of dopamine producing neurons in the substantia nigra and the presence of Lewy bodies in the substantia nigra and locus coeruleus. "Although an association between Dock5 and Parkinson’s disease has been suggested, the authors themselves noted that the Dock5 copy number variants were more likely to be variable numbers of tandem repeats as opposed to a typical copy number variation." (PMID 25309324, 2014).
viral infection (1 paper, 2017). "Although such a breakdown of cellular integrity can also be caused by viral infection and induced cell death, we are confident that such a scenario and the potential influence on the identified role of DOCK5 can be excluded." (PMID 29214055, 2017).
tumor (10 papers, 2010 to 2025). "Several candidate tumor suppressor genes that are less known to be implicated in human cancers include DOCK5 and CSMD1 map to this region." (PMID 22355333, 2012). "Fourteen of the mutated genes in this tumor are involved in metabolism (endogenous molecules as well as drugs), small molecule biochemistry, and cancer: AATF, ATF71P, CRIPAK, CROCC, CYP2A6, DOCK5, GPAT2, KRTAP4–9, LSM14A, MUC2, MYO1F, RHOQ, SUFU, and UTRN." (PMID 29259192, 2017). "To explore whether DOCK5 is required for invasion of cells in multicellular bodies – i.e. in tumour models, we generated spheroids and quantified cell invasion into 100% Matrigel." (PMID 40353692, 2025). "Alternative splicing is closely associated with tumour occurrence and progression, and our previous study characterized the landscape of alternative splicing in HNSCC, in which a novel DOCK5 variant was confirmed to play an oncogenic role in HNSCC cell proliferation, migration, and invasion." (PMID 37434235, 2023). "These include alterations in e.g. MSH4, PRDM2, and TP53I3 in the MSI tumor as well as GATA, DOCK5, and IGSF11 in the MSS tumor." (PMID 28683819, 2017). "Meanwhile, the oncogene DOCK5 variant plays a critical role in the human papilloma virus (HPV)-negative HNSCC and is involved in tumor proliferation, migration, and invasion." (PMID 32117741, 2020). "Besides the known tumor suppressor genes DOCK5 and PTEN, genes OXSR1, BSG, NT5E, PLEKHG7,CMTM8, NETO2, ODZ3, and ERBB4 adhered to our criteria and were qualified as novel candidate tumor suppressor genes." (PMID 25551557, 2014).
cancer (9 papers, 2012 to 2025). A tumor composed of atypical neoplastic, often pleomorphic cells that invade other tissues. "DOCK5 acts at focal adhesions in breast cells to establish positive feedback loops via CDC42 and RAC The stabilisation of polarity during migration promotes persistent YAP/TAZ activation which we propose drives cancer phenotypes." (PMID 40353692, 2025). "The qPCR results showed that KDM6A did not affect the DOCK5 and DOCK8 levels in T24 cells, indicating that KDM6A regulates Rac1 activity in a cancer type-dependent manner." (PMID 34006303, 2021).
infection (2 papers, 2017 to 2024). The state of being infected such as from the introduction of a foreign agent such as serum, vaccine, antigenic substance or organism. "Our network approach, combined with knockout data and comparative analysis between different genetic and infection scenarios, validates the causal role—be direct or indirect—of DOCK5 in these processes." (PMID 29214055, 2017). "The data showed Myo1c‐siRNA infection abrogated liraglutide‐induced Dock5 expression in parallel with cell viability, adhesion, and movement." (PMID 39159301, 2024). "After removing genes responding to MOCK infection from the DOCK5-ko DEG signatures in the case of infection, we performed enrichment tests of functional pathways." (PMID 29214055, 2017). "During infection, pathways that are up-regulated by the knockout of DOCK5 involve carbohydrate metabolism (FET p = 3.3e−4, 1.5-fold), in particular aminoglycan processes (FET p = 2.4e−3, 2.2-fold), lysosome functions (FET p = 5.8e−3, 2.1-fold), and phospholipid metabolism (FET p = 2.0e−2, 1.9-fold)." (PMID 29214055, 2017). "At day 1, neither ISG20 nor JUN showed significant difference between DOCK5-wt and DOCK5-ko cells during the infections but VAMP5 was already significantly down-regulated by DOCK5-ko (H1N1: p = 0.0056, 0.1-fold change; H3N2: p = 0.0020, 0.19-fold change)." (PMID 29214055, 2017). "The transcriptional program regulated by DOCK5 was characterized by sequencing mRNA from the cells of the representative clone DOCK5-c28 under different conditions as combinations of infection status (H1N1, H3N2, or Mock infection) and DOCK5 perturbation status (with or without DOCK5-ko)." (PMID 29214055, 2017).
kidney disease (2 papers, 2024 to 2025). "Next, to investigate the possible association between Dock5 and proteinuric kidney diseases, Dock5 expression was observed in patients (DKD and FSGS) and mouse models (db/db‐induced DKD mice and ADR‐induced FSGS mice)." (PMID 38161229, 2024). "Podocyte‐specific deficiency of Dock5 exacerbated podocyte injury and glomeruli pathology in proteinuric kidney disease." (PMID 38161229, 2024). "By querying the published datasets on kidney disease compiled in the Nephroseq database (nephroseq.org), we found that Dock5 expression was significantly lower in patients with DKD and FSGS than in healthy living donors." (PMID 38161229, 2024). "Interestingly, the effects of Dock5 deficiency were predominantly observed under disease conditions, but not under basal conditions, indicating that genetic determinants need to cooperate with environmental factors to drive proteinuric kidney disease initiation and progression." (PMID 38161229, 2024). "Podocyte‐specific deletion of Dock5 exacerbates podocyte injury and glomerular pathology in proteinuric kidney disease." (PMID 38161229, 2024). "The expression of Dock5 was reduced in both proteinuric kidney disease patients and mouse models." (PMID 38161229, 2024). "Moreover, the rescue of Dock5 expression ameliorated podocyte injury and proteinuric kidney disease." (PMID 38161229, 2024). "Finally, we investigated the effects of rescuing Dock5 expression on proteinuric kidney diseases." (PMID 38161229, 2024).
neurological diseases (1 paper, 2024). "It is possible that Elmo2 and Dock5 also exhibit specificity in certain types of neurological diseases." (PMID 38666924, 2024).
DOCK5 also shares sentences with these, for which no sentence is quoted: Insulin resistance (2 papers); acute myeloid leukemia (1); autism spectrum disorder (1); gastric cancer (1); lipid metabolism disorder (1); lung adenocarcinoma (1); melanoma (1); nephropathies (1); sarcopenia (1); steatosis (1); type 2 diabetes (1).